BTG1 (BTG anti-proliferation factor 1)
Diseases named in the same sentence as BTG1 in open-access papers (continued):
Sharing a sentence is not in itself a finding about the gene and the disease.
ovarian carcinoma (9 papers, 2013 to 2022). A malignant neoplasm originating from the surface ovarian epithelium. "In ovarian cancer, BTG1 expression caused a low growth rate, high cisplatin sensitivity, G1 arrest, apoptosis and decreased migration and invasion by down-regulating the expression of PI3K, PKB, Bcl-xL, survivin, VEGF, and MMP-2." (PMID 33330092, 2020). "Studies have shown that miR-27a-3p targets BTG1 to affect the biological phenotype of colorectal and ovarian cancer cells." (PMID 36741376, 2022). "BTG1 expression was lower in gastric, lung, breast and ovarian cancer than normal tissue due to its promoter methylation, which was the opposite to BTG1 expression." (PMID 36339000, 2022). "Here, we found that BTG1 expression was lower in gastric, lung, breast and ovarian cancer than normal tissue due to its promoter methylation, which was opposite of BTG1 expression." (PMID 36339000, 2022). "According to the cancer types of Kaplan-Meier plotter (before 2018), we chose gastric, lung, breast and ovarian cancers for BTG1 analysis." (PMID 36339000, 2022). "Then, we used xiantao database to perform bioinformatics analysis and found that BTG1 expression was lower in ovarian cancers than normal tissues (p < 0.05), in line with GEO data (GSE38666 and GSE26712)." (PMID 36339000, 2022). "Reportedly, the downregulated BTG1 expression is positively correlated with its promoter methylation in colorectal, gastric and ovarian cancers." (PMID 36339000, 2022). "Several studies have shown that BTG-1 expression is reduced in many tumors, including breast 20, hepatocellular 21, and ovarian cancers 22, and is closely related to the growth, metastasis, and invasion of tumors." (PMID 33531999, 2021). "BTG1 expression was restored after 5-aza-2′-deoxycytidine treatment in gastric, breast, and ovarian cancer cells, indicating that BTG1 promoter methylation accounted for its down-regulated expression in cancer cells." (PMID 33330092, 2020). "BTG1 functioned as a direct target of miR-330-3p and miR-27a-3p in hepatocellular carcinoma and ovarian cancer cells, respectively and thereby weakened cell viability, migration, and invasion and promoted cell apoptosis." (PMID 33330092, 2020). "There was higher expression of BTG1 mRNA in normal tissue than that in ovarian cancer tissue, and in benign tumors than in cancer tissue." (PMID 33330092, 2020). "We recently demonstrated that BTG1 expression is significantly reduced in ovarian carcinoma tissues, and that BTG1 silencing in ovarian carcinoma occurs through epigenetic repression." (PMID 31324015, 2019). "Beside, we found that the mRNA expression level of BTG1 varied with tumor type, such as lower in breast, colorectal and ovarian cancer and lung adenocarcinoma, higher in kidney, cervical and squamous cell lung cancer." (PMID 28922388, 2017). "Although the hypoexpression of BTG1 mRNA was found in ovarian, gastric, thyroid, hepatocellular, nasopharyngeal, esophageal, breast, and lung cancers, a genome-wide transcriptomic analysis showed an up-regulated BTG1 expression in ovarian cancer." (PMID 26050197, 2015). "BTG1 mRNA expression was detected in ovarian normal tissue (n = 17), ovarian benign tumors (n = 12), and ovarian carcinoma (n = 64) using real-time RT-PCR." (PMID 24084718, 2013). "A BTG1-expressing plasmid was transfected into ovarian carcinoma cells and their phenotypes and related proteins were examined." (PMID 24084718, 2013). "In this study, we describe the effects of BTG1 overexpression on the phenotypes and related proteins of ovarian carcinoma cells." (PMID 24084718, 2013). "The relationship between BTG1 expression and infiltrating immune cells in gastric, breast and ovarian cancer was opposite to that in lung cancer, which might be attributable to its inclusion of lung adenocarcinoma and squamous cell carcinoma." (PMID 36339000, 2022). "The correlation of BTG1 mRNA expression with clinicopathological features of ovarian cancer." (PMID 36339000, 2022).
ovarian carcinoma (continued). "BTG1 expression was positively associated with elder age, venous invasion, lymphatic invasion, and FIGO (International Federation of Gynecology and Obstetrics) staging of ovarian cancer (p < 0.05)." (PMID 36339000, 2022). "BTG1 mRNA expression was negatively correlated with FIGO staging of ovarian cancer." (PMID 33330092, 2020). "BTG1 mRNA expression was inversely related to FIGO staging of ovarian cancers." (PMID 26050197, 2015). "Nevertheless, the biological functions of BTG1 in ovarian carcinoma require further investigation." (PMID 24084718, 2013). "Altered BTG1 expression might play a role in the pathogenesis and progression of ovarian carcinoma by modulating proliferation, migration, invasion, the cell cycle, and apoptosis." (PMID 24084718, 2013). "Additionally, BTG-1 mRNA expression is negatively correlated with FIGO stage in ovarian cancer." (PMID 33531999, 2021). "In the present study, BTG1 mRNA expression was negatively linked to FIGO staging of ovarian carcinoma, indicating that BTG1 protein might be involved in the development of ovarian cancer and may be considered a good biomarker for indicating the aggressive behaviors of ovarian carcinoma." (PMID 24084718, 2013). "BTG1 mRNA expression in International Federation of Gynecology and Obstetrics (FIGO) stage I/II ovarian carcinomas was higher than that in FIGO stage III/IV ovarian carcinomas (p = 0.038)." (PMID 24084718, 2013). "BTG1 mRNA expression was not correlated with pathological classification or differentiation of ovarian carcinoma (p > 0.05)." (PMID 24084718, 2013).
colorectal cancer (8 papers, 2015 to 2022). A primary or metastatic malignant neoplasm that affects the colon or rectum. "However, it has also been reported that BTG1 expression is positively linked to aggressive features of colorectal cancer, including depth of invasion and/or lymph node metastasis." (PMID 36230852, 2022). "In summary, our study indicated that BTG1 expression might be positively linked to invasion, metastasis, and poor prognosis of colorectal cancers." (PMID 33330092, 2020). "BTG1 expression has been shown at lower levels in colorectal cancer than in the control, due to the hypermethylation of the BTG1 promoter." (PMID 36230852, 2022). "On the other hand, miR-27a promotes cell proliferation and suppresses apoptosis in colorectal cancer (CRC) by modulating BTG1." (PMID 36276982, 2022). "BTG1 overexpression suppressed tumor growth and lung metastasis of gastric and colorectal cancer cells by inhibiting proliferation, and enhancing autophagy and apoptosis in xenograft models." (PMID 36339000, 2022). "BTG1 has been shown as a direct target of piR-1245, suggesting an inverse correlation between BTG1 expression and piR-1245 in colorectal cancer." (PMID 36230852, 2022). "In colorectal cancer, miR-27a-3p has been reported to be upregulated in tumor tissues and to facilitate tumor progression by inhibiting the tumor suppressor gene BTG1." (PMID 34389030, 2021). "BTG1 induced Beclin-1-dependent autophagy and weakened β-catenin pathway in colorectal cancer cells." (PMID 33330092, 2020). "BTG1 expression should be employed to indicate the aggressive behaviors and worse prognosis of colorectal cancer." (PMID 33330092, 2020). "In the present study, we mainly investigated the roles of BTG1 expression on progression of colorectal cancers." (PMID 33330092, 2020). "Among them, cg08832851 and cg05819371 hypermethylation and mRNA expression of BTG1 were positively related with poor prognosis of the colorectal cancer patients (P < 0.05)." (PMID 33330092, 2020). "BTG1 mRNA expression was negatively correlated with its promoter methylation in colorectal cancer (P < 0.05)." (PMID 33330092, 2020). "Here, we found that ectopic BTG1 expression reduced the mRNA and protein expression of β-catenin and down-regulated its phosphorylation in colorectal cancer cells." (PMID 27447746, 2017). "According to its frequency and density, BTG1 expression was statistically higher in colorectal cancer and adenoma than adjacent NNM (p<0.05)." (PMID 27447746, 2017). "Only 5.6% (2/36) cases showed BTG1 mRNA overexpression in colorectal cancer, compared with matched mucosa." (PMID 27447746, 2017). "Densitometry analysis indicated that BTG1 protein was more detected in colorectal cancer than that in NNM (p<0.05)." (PMID 27447746, 2017). "The correlation between BTG1 methylation and mRNA expression in colorectal cancer." (PMID 33330092, 2020). "Our previous work also showed that BTG1 overexpression might in vivo and in vitro reverse the aggressive phenotypes of colorectal cancer cells." (PMID 33330092, 2020). "However, BTG1 hypermethylation at cg05819371 and cg08832851 was significantly related with poor prognosis of the colorectal cancer patients (P < 0.05)." (PMID 33330092, 2020). "We conducted a GSEA to analyze BTG1-related signal pathways in colorectal cancer." (PMID 33330092, 2020). "Taken together, it was suggested that BTG1 expression might be involved in the progression of colorectal cancer and be considered as a good marker to indicate the aggressive behaviors of colorectal cancer." (PMID 33330092, 2020). "Relationship between BTG1 expression and clinicopathological features of colorectal cancer." (PMID 33330092, 2020). "In colorectal cancer cells, BTG1 might suppress proliferation and tumor growth and induce apoptosis and differentiation, which resulted in a higher anchoring of CEA to membrane, a low necrosis and subsequent release of CEA into the blood vessel." (PMID 33330092, 2020).
colorectal cancer (continued). "Survival curves for colorectal cancers were stratified according to BTG1 expression." (PMID 33330092, 2020). "BTG1 expression might reverse aggressive phenotypes and be employed as a target of gene therapy for colorectal cancer." (PMID 27447746, 2017). "Finally, the in vivo effects of BTG1 overexpression on tumor growth of colorectal cancer cells were assessed in nude mice." (PMID 27447746, 2017). "Thus, the most possible explanation for this paradoxical phenomenon was BTG1 mRNA destabilization and feedback overexpression of BTG1 protein in colorectal cancer cells." (PMID 27447746, 2017). "In agreement with the findings in breast, lung, ovarian and hepatocellular cancers, our functional experiments showed that BTG1 overexpression suppressed proliferation, cell cycle progression and induced apoptosis, autophagy and differentiation in colorectal cancer cells." (PMID 27447746, 2017). "Among 36 colorectal cancers, 25 cancers overexpressed 19kDa BTG1 protein in comparison to NNM." (PMID 27447746, 2017). "In addition, the effects of BTG1 overexpression on aggressive phenotypes of colorectal cancer cells were analyzed with phenotype-related molecules examined." (PMID 27447746, 2017). "In addition, colorectal metastatic cancer cells in the lymph nodes has shown more BTG1 expression than that in the primary cancer site, suggesting that the overexpression of BTG1 might promote the invasion and/or metastasis of the colorectal cancer." (PMID 36230852, 2022). "BTG1 overexpression might weaken β-catenin pathway in colorectal cancer cells." (PMID 27447746, 2017). "Here, BTG1 overexpression inhibited proliferation, induced differentiation, autophagy, and apoptosis in colorectal cancer cells (p2 arrest might be related to Cyclin B1 and Cdc25B hypoexpression in HCT-15 transfectants, while G1 arrest in HCT-116 transfectants overexpressing p21 and p27." (PMID 27447746, 2017). "In colorectal cancer, miR-22 was recognised to affect drug sensitivity properties to 5-fluorouracil treatments through its involvement in the regulation of autophagy mechanisms, mainly due to miR-22 direct action on B-cell translocation gene 1 (BTG1) — a key molecular player in autophagy." (PMID 25973145, 2015). "BTG1 expression was found to positively correlate with depth of invasion, venous invasion, lymph node metastasis, distant metastasis, and TNM staging of colorectal cancer (P < 0.05) but negatively with serum levels of CEA and CA19-9 (P < 0.05)." (PMID 33330092, 2020). "To clarify the effects of BTG1 on the invasion and metastasis of colorectal cancer cells, we overexpressed it in HCT-15 cells and found that BTG1 weakened adhesion, but enhanced the ability to migrate and invade." (PMID 33330092, 2020). "In the present study, we found that BTG1 overexpression up-regulated the expression of ATG7, ATG14 and Beclin-1 in both colorectal cancer cells." (PMID 27447746, 2017). "The chemosensitivity of BTG1 transfectants to paclitaxel, cisplatin, MG132 (proteasome inhibitor) or SAHA (histone deacetylase inhibitor) was positively correlated with its apoptotic induction of colorectal cancer cells." (PMID 36339000, 2022). "Statistically, the BTG1 mRNA expression was decreased in colorectal cancer, in comparison with paired non-neoplastic mucosa (NNM, p<0.05)." (PMID 27447746, 2017). "BTG1 expression was positively related to depth of invasion, venous invasion, lymph node metastasis, distant metastasis, and TNM staging (P < 0.05) but not correlated with age, sex, lymphatic invasion, liver metastasis, or differentiation of colorectal cancer (P > 0.05)." (PMID 33330092, 2020).
cervical cancer (7 papers, 2020 to 2025). A primary or metastatic malignant neoplasm involving the cervix. "Lidocaine suppressed proliferation and induced cell apoptosis of cervical cancer cells by modulating the genes expression of lncRNA-MEG3/BTG1." (PMID 34249706, 2021). "Lidocaine enhances apoptosis and reduces proliferation of cervical cancer cells by targeting the lncRNA MEG3/miR-421/BTG1 axis." (PMID 34122108, 2021). "Compared with normal tissues, BTG1 expression was increased in brain and CNS cancer, cervical cancer, head and neck cancer, kidney cancer, and other cancers." (PMID 33041670, 2020). "miR-141-5p can affect cervical cancer cell proliferation and apoptosis by targeting BTG1." (PMID 36553664, 2022). "TCL1A and BTG1, which are highly expressed in B cells from early CRC tumor, are reported as tumor suppressors in cervical cancer and CRC, respectively." (PMID 33463049, 2021).
hepatocellular carcinoma (7 papers, 2017 to 2025). A malignant tumor that arises from hepatocytes. "BTG1 downregulation is also seen in hepatocellular carcinoma and is significantly associated with disease-specific and relapse-free survival." (PMID 33041670, 2020). "By inhibiting BTG1, miR-511 can strengthen the proliferation of human hepatoma cells, while miR-301 can promote the development of colitis-associated cancer." (PMID 40918450, 2025). "In hepatocellular carcinoma, miR-330-3p enhanced cancer cells’ viability, migration, invasion, and apoptosis resistance by binding to BTG1." (PMID 37048561, 2023). "In hepatocellular carcinoma (HCC), lower expression levels of BTG1 mRNA and protein have been correlated with significantly improved survival rates." (PMID 41285707, 2025). "In addition, the BTG1 may function as a direct target of miR-330-3p in hepatocellular carcinoma, which could reduce the cell viability, migration, and/or invasion, whereas promoting cancer cell apoptosis." (PMID 40918450, 2025).
lymph node metastasis (7 papers, 2015 to 2022). "In our previous study, downregulation of BTG1 was associated with larger tumor size and lymph node metastasis." (PMID 29721160, 2018). "The Cox’s risk proportional analysis showed that younger age, lymph node metastasis, TNM staging and BTG1 hypoexpression were independent factors for worse prognosis of the patients with lung cancer (p < 0.05)." (PMID 36339000, 2022). "A body of evidence indicates that BTG1 expression is negatively correlated with tumor invasion, lymph node metastasis, the clinical stage, and/or a low survival rate in patients with various cancers." (PMID 36230852, 2022). "BTG1 expression was positively correlated with depth of invasion, lymphatic and venous invasion, lymph node metastasis, TNM staging and worse prognosis (p < 0.05)." (PMID 26050197, 2015). "Low plasma exosome-derived BTG-1 levels were observed in the poor differentiation group and were associated with abnormal CEA levels, tumor diameter greater than or equal to 5 cm, stage III disease, and lymph node metastasis." (PMID 33531999, 2021). "BTG1 expression was positively correlated with depth of invasion, lymphatic and venous invasion, lymph node metastasis, and TNM staging (p < 0.05), but not with distant metastasis (p > 0.05)." (PMID 26050197, 2015).
acute lymphoblastic leukemia (6 papers, 2012 to 2022). Leukemia with an acute onset, characterized by the presence of lymphoblasts in the bone marrow and the peripheral blood. "B-cell Translocation Gene 1 (BTG1) is a tumor suppressor that is frequently deleted in acute lymphoblastic leukemia and recurrently mutated in diffuse large B cell lymphoma." (PMID 26657730, 2016). "Pediatric B-cell precursor acute lymphoblastic leukemia (BCP-ALL) is associated with a high frequency of copy number alterations (CNAs) in IKZF1, EBF1, PAX5, CDKN2A/B, RB1, BTG1, ETV6, and/or the PAR1 region (henceforth: B-cell development genes)." (PMID 30874617, 2019). "We and others have shown that BTG1 is affected by monoallelic deletion in about 9% of childhood pre-B acute lymphoblastic leukemia (B-ALL) cases, and that existing or novel BTG1 copy number aberrations can be detected at relapse." (PMID 26657730, 2016). "In B‐cell precursor acute lymphoblastic leukemia (BCP‐ALL), the most common type of cancer in children, microdeletions affecting BTG1, but not BTG2, are recurrently detected." (PMID 30350856, 2019). "BTG1 downregulation was reported to result from genomic deletions, which were detected in 9% (65/722) of B-cell precursor acute lymphoblastic leukemia (ALL), but not in 109 cases of T-cell ALL." (PMID 24084718, 2013).
prostate carcinoma (6 papers, 2013 to 2021). A carcinoma that arises from epithelial cells of the prostate gland. "Intriguingly, increased expressions of ABCB6, BTG1 and EPB41L4B were found in glioma, thyroid carcinoma and prostate cancer, respectively, but the underlying mechanism stays unclear." (PMID 25575809, 2015). "MiR-19a-3p targets BTG1 and regulates apoptosis of castration-resistant prostate cancer cells." (PMID 32733254, 2020).
colon cancer (5 papers, 2007 to 2022). "The low expression of BTG1 in colon cancer is related to the clinicopathological characteristics, postoperative recurrence and survival of patients." (PMID 33041670, 2020). "miR-27a-3p regulates the proliferation and apoptosis of colon cancer cells by potentially targeting BTG1." (PMID 33041670, 2020). "The cumulative survival rate of BTG1-positive patients with colon cancer is significantly higher than that of BTG1-negative patients." (PMID 36230852, 2022).
lung carcinoma (5 papers, 2015 to 2022). "According to xiantao and UALCAN databases, BTG1 expression was lower in lung cancer than in normal tissue p < 0.05)." (PMID 36339000, 2022). "BTG1 methylation was higher in lung cancer than in normal tissues by UALCAN (p < 0.05)." (PMID 36339000, 2022). "In addition, the expression of BTG1 in lung cancer was increased in one study and decreased in two studies." (PMID 33041670, 2020). "Second, this study did not discuss plasma exosome-derived BTG-1 levels in patients with other types of lung cancer." (PMID 33531999, 2021).